RN7SKP261 (RN7SK pseudogene 261)
Gene: Miscellaneous RNA gene on chromosome 12 (80,343,515 to 80,343,792, reverse strand). Ensembl gene ENSG00000222880.
Homologues: Orthologues: chimpanzee 7SK (98% identical), guinea pig 7SK (22% identical). Paralogues in human: RN7SKP79 (78% identical), 7SK (77% identical), RN7SKP255 (77% identical), RN7SKP87 (77% identical), RN7SKP180 (77% identical), RN7SKP90 (76% identical), RN7SKP176 (76% identical), RN7SKP203 (76% identical), RN7SKP222 (76% identical), RN7SKP47 (76% identical), RN7SKP71 (76% identical), RN7SKP75 (76% identical), and 284 more.